JAK2 (Janus kinase 2)
Diseases named in the same sentence as JAK2 in open-access papers (continued):
Sharing a sentence is not in itself a finding about the gene and the disease.
anemia (continued). "As expected, based on the mechanism of action of ruxolitinib as a JAK1/JAK2 inhibitor, thrombocytopenia and anemia occurred in most patients treated with ruxolitinib." (PMID 28228106, 2017). "The presence of JAK2 mutations is common in MPN and is also frequent in cases with refractory anemia with ring sideroblasts associated with marked thrombocytosis (RARS-T)." (PMID 27127180, 2016). "As expected, given the mechanism of action of ruxolitinib as a JAK1/JAK2 inhibitor, the most common hematologic AEs were anemia and thrombocytopenia, but these rarely led to treatment discontinuation." (PMID 27211272, 2016). "Analysis of the peripheral blood revealed significantly reduced numbers of platelets and marked microcytic hypochromic anemia and the hematocrits of the Jak2 cKO mice were reduced by ∼85%, when compared to controls." (PMID 23544085, 2013). "The most commonly observed adverse events (AEs) in the phase III trials were dose-dependent anemia and thrombocytopenia, which were anticipated as thrombopoietin and erythropoietin signal through JAK2." (PMID 24283202, 2013). "The most common adverse events were dose-dependent anemia and thrombocytopenia, which were anticipated because thrombopoietin and erythropoietin signal through JAK2." (PMID 24283202, 2013). "Our results here demonstrate that virtual elimination of wild type Jak2 activity can ultimately lead to severe anemia/thrombocytopenia and even death." (PMID 23544085, 2013). "Socs2, plus five additional targets, further proved to comprise new EPOR/Jak2/Stat5 response genes (which are important for erythropoiesis during anemia)." (PMID 22808010, 2012). "A third central EPOR signaling route involves a Jak2-plus-Stat5 axis which has been shown to be important for EPO-dependent erythropoiesis during anemia." (PMID 22808010, 2012). "Jak2 inhibitors are indeed able to induce a dramatic decrease in spleen size in thalassemic animals with a limited effect on anemia." (PMID 20508726, 2010). "For instance, elevated CXCL10 expression was observed in patients with interstitial lung disease (ILD), leukopenia, and anemia; JAK2 expression differed in rheumatoid arthritis comorbidity; IFIH1 expression also showed differences in those with Raynaud's phenomenon and ILD." (PMID 41929488, 2026). "The use of alternative JAK2 inhibitors, which have been shown to have reduced hematological toxicity or even the potential to benefit anemia, could also be considered." (PMID 39831987, 2025). "Further studies are also required to assess the impact of this drug on other myeloid neoplasms associated with anemia such as myelodysplastic syndromes with ring sideroblasts or SF3B1 mutation, especially those with co-expression of a JAK2 mutation and thrombocytosis." (PMID 38983933, 2024). "Additionally, IL-6 and other inflammatory cytokines induce the expression of hepcidin by the pathway JAK2/STAT3, causing anemia of inflammation." (PMID 38396414, 2024). "For instance, although upadacitinib is a JAK1-selective inhibitor, the incidence of anemia, one of the adverse effects of JAK2 inhibition, was higher in patients treated with 30 mg of upadacitinib than in those treated with 15 mg of upadacitinib or placebo during 16 weeks." (PMID 38975347, 2024). "CEP-33779, a small molecular inhibitor of JAK2, rescued the anemic phenotype, which may be a candidate therapeutic drug for anemia." (PMID 37106740, 2023). "On the other hand, patients receiving ruxolitinib were more likely to be younger (p = 0.02), males (p = 0.01), JAK2 mutated (p = 0.04), belong to DIPSS-plus intermediate risk group (p < 0.01), and less likely to present with transfusion-dependent anemia (p < 0.01)." (PMID 36599841, 2023). "Because JAK2 inhibition also has toxic effects (e.g., anemia, thrombocytopenia) that prevent many patients from obtaining the quality-of-life benefits from agents such as ruxolitinib, critical to such combination therapies will be the tolerability of the treatment regimen." (PMID 35082276, 2022).
anemia (continued). "As JAK2 inhibition is thought to be affiliated with the AEs of anemia seen in patients taking tofacitinib and baricitinib, likely due to JAK2′s role in erythropoiesis, it was suggested that upadacitinib’s purported JAK1-selectivity would reduce rates of anemia." (PMID 35056105, 2021). "These cytokines are indispensable for hematopoietic stem cell differentiation and proliferation; thus, potential significant side effects of JAK2 inhibitors may include anemia, thrombocytopenia, and neutropenia." (PMID 33830087, 2021). "Moreover, in a recent phase 2 trial, the JAK1/JAK2 inhibitor momelotinib has shown efficacy in the anemia of MF and a phase 3 trial comparing this drug with danazol is currently in progress." (PMID 34017073, 2021). "Though ultimately efficacious at both 15 mg and 30 mg, dose-dependent side effects emerged: In the SELECT-BEYOND trial, some patients receiving the highest dosages (30 mg/day) experienced a reduction in hemoglobin levels and subsequent anemia characteristic of JAK2 inhibition." (PMID 34122106, 2021). "When JAK2 signaling is inhibited in patients who received the treatment with ruxolitinib, it may lead to impaired erythropoiesis and anemia." (PMID 32333155, 2020). "Because JAK2 signals downstream of GM-CSF, EPO, and TPO, JAK1 selective inhibitors are expected to have a better safety profile than JAK1/JAK2 inhibitors with a lower risk of anemia." (PMID 33343569, 2020). "For instance, significant inhibition toward JAK2 leads to anemia." (PMID 31849996, 2019). "On the other side, the causes of reactive thrombocytosis, such as iron deficiency anemia and autoimmune diseases, are more common in the middle-aged women and also JAK2 mutation is negative." (PMID 29732039, 2018). "One prior report demonstrated that AMPK may interact with SOCS1 by inducing JAK2 degradation in anemia-induced inflammation." (PMID 30213073, 2018). "Similar to our case, their patient had leukoerythroblastosis, anemia, splenomegaly, and a negative JAK2 mutation." (PMID 23781354, 2013). "Compared to controls, the fetal livers from the Jak2 cKO embryos were smaller and had hematopoietic insufficiency characterized marked hypo-cellularity, reductions in erythroid and megakaryocytic precursors, and severe anemia." (PMID 23544085, 2013). "In a mouse model of JAK2 V617F-driven polycythemia, low dose aconitase inhibition rapidly normalized red cell counts in a lineage specific manner without causing anemia." (PMID 21887333, 2011). "It is appealing to speculate that β-thalassemia intermedia patients affected by splenomegaly could be treated temporarily with Jak2 inhibitors so as to reduce the spleen size and, in the presence of blood transfusions, to prevent further anemia." (PMID 20508726, 2010). "Additionally, advantages of using ritlecitinib may avoid side effects of pan-JAK inhibitors, such as increased cholesterol and liver enzymes, and those related to JAK2 inhibition, including thrombocytopenia and anemia." (PMID 41488086, 2025). "Thus, the use of JAK2 inhibitors for β-thalassemia might be desirable, but it would require careful optimization, noting the potential for off-target immune suppression, as well as the anemia that would be expected from continuous JAK2 inhibition." (PMID 34766559, 2021). "The contradiction between correction of anemia and creation of anemia in this study is therefore explained by the fact that we studied two molecules with slightly different modes of action, baricitinib being a more significant inhibitor of JAK2 than tofacitinib." (PMID 33081099, 2020). "Furthermore, we found inhibitors of JAK2 or STAT3 phosphorylation could rescue anemia in rpl18 mutants." (PMID 32075953, 2020). "In addition to ET and PMF patients, CALR mutations have also been observed in 3(13.0%) of 24 patients with refractory anemia with ringed sideroblasts and marked thrombocytosis; none of the 3 patients had JAK2 or MPL mutations." (PMID 27486987, 2016).
anemia (continued). "Consistent with previous reports and the mechanism of action of ruxolitinib as a potent JAK2 inhibitor, median hemoglobin levels in the ruxolitinib arm decreased over the first 12 weeks of treatment and then recovered to greater than the 100-g/l threshold considered to be the criterion for anemia." (PMID 27211272, 2016). "In these settings, the use of Jak2 inhibitors would be expected to limit or reduce splenomegaly, thereby preventing or delaying the need for splenectomy and indirectly improving the management of anemia and iron overload by reducing the rate of blood transfusions." (PMID 20508726, 2010). "In conclusion, the use of Jak2 inhibitors for β-thalassemia might be desirable, but it would require a careful optimization noting the potential for off-target immune suppression, as well as the anemia that would be expected from continuous Jak2 inhibition." (PMID 20508726, 2010). "The polycythemia induced by JAK2 V617F was maximal at 3 to 4 months post-transplantation, but tended to decrease with time in both strains, with hematocrit and reticulocyte counts returning to nearly normal ranges by 7 to 8 months after transplantation, and some mice developing overt anemia." (PMID 17183644, 2006). "In the phase 3 trials of both the JAK1/JAK2 inhibitor ruxolitinib and JAK2/FLT3 inhibitor fedratinib, indicators of anemia worsening such as decreased mean hemoglobin levels and increased transfusions were evident in the initial weeks of treatment." (PMID 39682250, 2024). "MMB’s unique inhibition of JAK1, JAK2, and ACVR1/ALK2, a key player in iron homeostasis, leads to decreased hepcidin and increased serum iron availability, contributing to considerable anemia benefits." (PMID 38983933, 2024). "Thrombocytopaenia, anaemia and neutropenia, resulting from inhibition of the JAK2‐signalling thrombopoietin, erythropoietin and G‐CSF/GM‐CSF respectively, have been described, which promotes the notion that selectivity against JAK2 may be desirable to improve safety." (PMID 37275428, 2023). "Momelotinib, a JAK1/JAK2 inhibitor with additional activity against ACVR1, is in late-stage clinical development and is hoped to address the unmet need of anemia in patients with MF." (PMID 37345196, 2023). "Our results showed that Ba/F3 TpoR JAK2 V617F cells can propagate in vivo in nude mice leading to accumulation of GFP-positive cells and anaemia, thrombocytopenia, splenomegaly and hepatomegaly." (PMID 24251790, 2013). "PMF, one of the most complex and rare malignant tumors in MPNs, is frequently but not always accompanied by JAK2, CALR mutation, aberrant cytokine expression, bone marrow fibrosis and anemia, etc.." (PMID 34633991, 2021). "Supporting the role of JAK2-inhibition in the pathogenesis of anemia, a phase II study found that deucravacitinib did not significantly alter levels of lymphocytes, NK cells, neutrophils, platelets, or hemoglobin." (PMID 35056105, 2021). "Unlike other JAK2 inhibitors, momelotinib appeared to improve anemia, a result reproduced in another trial investigating long-term use in 60 patients." (PMID 31244289, 2019). "It is now well-established that momelotinib treatment in MF provides relief from symptomatic splenomegaly and constitutional symptoms, and unlike most other JAK2 inhibitors, also improves anemia in a substantial fraction of patients." (PMID 29515114, 2018). "Based on these data, WT1 is a useful marker of disease and of response to JAK2 inhibitors especially for patients without blasts and for patients who develop anemia or thrombocytopenia not for progression but as therapy‐related toxicity." (PMID 27167495, 2016). "The current study presents the case of a 63-year-old patient exhibiting refractory anemia with ringed sideroblasts associated with marked thrombocytosis (RARS-T), who was positive for the MPL W515L mutation, but negative for the JAK2 V617F mutation." (PMID 25621045, 2015).
anemia (continued). "These inhibitors do not discriminate between wild-type and mutant JAK2, and can induce unwanted effects, such as anemia and thrombocytopenia." (PMID 20585391, 2010). "In MF patients, disease-related anemia can be exacerbated by treatment with ruxolitinib because of myelosuppression, an adverse event that is consistent with the drug’s interference with erythropoietin signaling via JAK-STAT (especially JAK2), which is essential for erythropoiesis." (PMID 35045875, 2022). "In this setting, increasing the dose of ruxolitinib to treat splenomegaly and symptoms may not be a viable option because it would further accentuate anemia given the essential role of JAK2-mediated erythropoietin signaling in erythropoiesis." (PMID 35045875, 2022). "Anemia observed after upadacitinib treatment (selective JAK1 inhibitor) may suggest that this drug also inhibits JAK2, particularly when used in high dosage (IC50 = 0.043 μM for JAK1 vs. IC50 = 0.2 μM for JAK2)." (PMID 32796683, 2020). "The mechanism behind this unexpected benefit of a JAK2 inhibitor was poorly understood until momelotinib was shown to down-regulate hepatic hepcidin production via antagonism of the type 1 activin receptor (ACVR1/ALK2) and ameliorate anemia in a rodent model of anemia of chronic disease." (PMID 32903304, 2020). "The reason why it improves anemia is probably because that the half-life of ESAs is longer than of ruxolitinib’s, and JAK2 is maybe not completely inhibited by therapeutic concentrations of ruxolitinib." (PMID 32333155, 2020). "Furthermore WT1 is a good marker of response to JAK2 inhibitors especially for patients without blasts and for patients who develop anemia or thrombocytopenia not for progression but as therapy related toxicity." (PMID 27167495, 2016). "ICT therefore may have a role in the management of anemia in PMF, in all stages of the disease, in patients treated with conventional cytoreductive therapy but especially in consideration of new drugs that are now used in this setting, ie JAK2 inhibitors." (PMID 24959339, 2014). "Jak2 is critical for murine embryogenesis as mice lacking Jak2 expression die of anemia at E12.5." (PMID 24086539, 2013). "Considering the crucial role of JAK2 during erythropoiesis, it is therefore tempting to hypothesize that the anaemia observed in patients treated with HDAC6i in vivo, and the defect in erythroid differentiation that we observed in vitro are related to an altered HSP90/JAK2 axis." (PMID 36578217, 2023). "The JAK1/JAK2 inhibitor momelotinib, currently under investigation for patients with MF and anemia, has potent inhibitory activity against ACVR1/ALK2 and may become a second-line treatment option for patients who have to eventually stop ruxolitinib due to excessive anemia." (PMID 36786879, 2023). "However, it was less efficient in reducing stressed erythropoiesis in the PTMF model and did not correct the anaemia, as we showed for the JAK1/2 inhibitor Momelotinib 28, possibly because of its JAK2 specificity." (PMID 26176817, 2015). "Furthermore, the clinical viability of JAK2 PROTACs is yet to be determined and, in the absence of PROTAC ligands specific for mutant-JAK2 or JAK2 fusions, JAK2 PROTACS may induce anemia and thrombocytopenia due to degradation of WT JAK2, therefore, further investigations are required." (PMID 35903543, 2022).
Splenomegaly (114 papers, 2006 to 2026). Abnormal increased size of the spleen. "The current study provides real-world observations in CALR-mutated MF patients with splenomegaly and/or symptoms requiring therapy with JAK2 inhibitors." (PMID 39831987, 2025). "The prevalence of splenomegaly was comparable between JAK2- (36.8%) and CALR-mutated patients (61.1%; p = 0.19), and follow-up assessments were performed at 12 and 24 months." (PMID 41463191, 2025). "In JAK2-V617F transgenic mice, the loss of just a single Hmga1 allele was sufficient to dampen erythrocytosis and thrombocytosis while preventing splenomegaly, osteosclerosis, and myelofibrosis." (PMID 40076747, 2025). "The myelodepletive phenotype is usually associated with primary MF, ≥2 cytopenias, modest splenomegaly, lower JAK2 V617F burden, higher fibrosis, greater genomic complexity, and inferior OS." (PMID 37444441, 2023). "In most countries, the JAK2-inhibitor ruxolitinib is currently reimbursed only for MF patients with intermediate- or high-risk disease in order to control systemic symptoms or splenomegaly." (PMID 37835392, 2023). "With the discovery of the JAK2 inhibitors, the use of ruxolitinib has been associated with significant improvements in disease-associated symptoms and splenomegaly." (PMID 35455686, 2022). "Relationships between hepcidin, GDF15, and mitoferrin-1 levels and presence of JAK2 mutation and splenomegaly." (PMID 30761871, 2019). "When hepcidin, GDF15 and mitoferrin-1 levels were analyzed according to the presence of JAK2 mutation and splenomegaly, it was found that hepcidin levels were significantly lower in the patients with JAK2 mutation (P = 0.007)." (PMID 30761871, 2019). "In patients of PV and ET JAK2 V617F mutation has been associated with advanced age mostly above 40 years, high hemoglobin, high platelet count and marked palpable splenomegaly." (PMID 31870101, 2019). "JAK2 mutational status or allele burden have been related to clinical signs of the disease like splenomegaly, transformation to Acute Myeloid Leukemia (AML) and overall survival, thus pointing to JAK2 inhibition as a promising strategy to treat MF." (PMID 29455651, 2018). "Leukocyte counts, hemoglobin values and the presence of splenomegaly were significantly different in patients with JAK2 mutation." (PMID 29732039, 2018). "Here, we report two elderly MF patients with massive splenomegaly and JAK2 V617F mutation who successfully underwent splenic irradiation prior to allogeneic HCT with the RIC regimen." (PMID 27840748, 2016). "Similar to JAK2-V617F mice with global, heterozygous Hmga1 deficiency, those with the loss of one Hmga1 allele restricted to HSCs have decreased erythrocytosis, thrombocytosis, splenomegaly, and fibrosis." (PMID 40076747, 2025). "Oral fedratinib therapy (200 mg a day, owing to JAK-2 pathogenic gene variants) was continued, because the association between fedratinib and uveitis was initially nuclear and fedratinib was effective for splenomegaly." (PMID 40276423, 2025). "MF is characterized by splenomegaly, as well as severe systemic symptoms including extreme fatigue, shortness of breath, nighttime sweating, weight loss, fever, and bone pain, usually with JAK2, CALR, or MPL mutations." (PMID 40860801, 2025). "The germline mutation JAK2 L604F is the likely cause of splenomegaly at birth." (PMID 37639050, 2023). "In addition, some found that the ≥2% cut-off for JAK2 V617F allele burden was of clinical interest as such patients were more likely to present with splenomegaly and evolve towards MPN within first year of follow up." (PMID 37370982, 2023). "This is more likely associated between the JAK2 mutation and splenomegaly." (PMID 29732039, 2018).